RNY1P16 (RNY1 pseudogene 16)
Gene: Miscellaneous RNA gene on chromosome 12 (101,719,808 to 101,719,918, forward strand). Ensembl gene ENSG00000199933.
Homologues: Orthologues: chimpanzee Y_RNA (100% identical), macaque Y_RNA (86% identical), mouse Gm26329 (77% identical). Paralogues in human: Y_RNA (80% identical), RNY1 (79% identical), Y_RNA (79% identical), Y_RNA (78% identical), RNY1P11 (77% identical), RNY1P5 (77% identical), Y_RNA (77% identical), Y_RNA (76% identical), Y_RNA (75% identical), RNY1P4 (74% identical), RNY1P8 (74% identical), Y_RNA (74% identical), and 88 more.